JAK2 (Janus kinase 2)
Diseases named in the same sentence as JAK2 in open-access papers (continued):
Sharing a sentence is not in itself a finding about the gene and the disease.
myelodysplastic syndrome (32 papers, 2007 to 2026). A clonal hematopoietic disorder characterized by dysplasia and ineffective hematopoiesis in one or more of the hematopoietic cell lines. "A third study included 88 cases with myelodysplastic syndrome and an isolated del(5q) in which 5 cases (6.4% of total cases) revealed concurrent JAK2 V617F mutations." (PMID 36810551, 2023). "In this manuscript we attempt to investigate and characterize JAK2 mutations in myelodysplastic syndrome (MDS)." (PMID 36810551, 2023). "In this manuscript, we presented three unique cases of myelodysplastic syndrome with diverse JAK2 mutations." (PMID 36810551, 2023). "This is the report of the clinical case of a patient who presents the association of a JAK-2 positive chronic myeloproliferative neoplasia to a subsequent 5q- myelodysplastic syndrome, developed after about 14 years from the first diagnosis." (PMID 27872730, 2016). "In addition, we found JAK2 R564L and JAK2 I670V point mutation variants to be associated with the other two cases with a myelodysplastic syndrome phenotype." (PMID 36810551, 2023). "Second, JAK2 mutations are diverse and JAK2 variant mutations may lead to a myelodysplastic syndrome phenotype." (PMID 36810551, 2023). "Clonal heterogeneity was also shown in MPNs with del(20q) and myelodysplastic syndromes (MDS) with isolated del(5q) and positive JAK2 V617F mutation." (PMID 31555600, 2019). "Infrequent occurrence of this unique JAK2 mutation has been reported in chronic myelomonocytic leukemia (CMML), atypical or unclassified myeloproliferative disorder (MPD), myelodysplastic syndrome (MDS), systemic mastocytosis (SM), and chronic neutrophilic leukemia (CNL)." (PMID 28422729, 2017). "Based on the morphology, immunology, cytogenetics, and molecular biology of bone marrow cells, the patient was diagnosed with myelodysplastic syndrome (MDS, +8, -7, IPSS-R 5.5 points, JAK2, ROBO2, and CROCC mutations)." (PMID 40881710, 2025). "Of these non-JAK2 mutation cases, the NRAS, CSF3R and TET2 c.4319_4329del; p.Arg1440Hisfs*34 were in the context of therapy-related disease; the remaining 4 other mutations (TET2, TET2, DNMT3A, and SF3B1) were in the context of disease progression from myelodysplastic syndrome." (PMID 36323674, 2022). "Erlotinib was shown to decrease phosphorylation of JAK2 and STAT-5 in EGFR-negative myelodysplastic syndrome (MDS) cell lines KG-1 and erlotinib can disrupt signaling of the JAK2/STAT-5 pathway." (PMID 22436374, 2012). "Moreover, a colony assay targeting a patient with myelodysplastic syndrome (MDS)/MPN-RS-T harboring both JAK2 exon 12 (p.H538_K539delinsL) and SF3B1E622D mutations demonstrated that SF3B1-mutated clones existed in isolation but all clones with JAK2 exon 12 mutations had accompanying SF3B1 mutations." (PMID 37629188, 2023). "Another study reported that chidamide inhibited the viability of myelodysplastic syndrome and AML cells by suppressing JAK2/STAT3 signaling or inducing apoptosis via the accumulation of DNA damage and repair defects in AML stem and progenitor cells." (PMID 31850196, 2019).
cardiac hypertrophy (31 papers, 2013 to 2025). "A number of studies have shown that inhibition of cardiac hypertrophy and remodelling in different experimental models is associated with inhibition of JAK2/STAT3 activity." (PMID 38256208, 2024). "Cardiac hypertrophy and fibrosis are associated with the activation of the JAK2/STAT3 signaling pathway." (PMID 36671504, 2023). "Modern studies have shown that JAK2/STAT3 signaling pathway activation is associated with cardiac hypertrophy; it is one of the important pathways of cardiac apoptosis and is of great significance in cardiomyocyte signal transduction pathways." (PMID 34221090, 2021). "FNDC5 ameliorated HFD-induced cardiac hypertrophy, via the effects on inflammation, oxidative stress and NFκB activation, in association with JAK2/STAT3 signaling inhibition." (PMID 30940158, 2019). "Third, the underlying mechanism by which HSF1 attenuated ischaemia‐induced cardiac hypertrophy is associated with the blockage of the JAK2/STAT3 pathway." (PMID 29992755, 2018). "Moreover, CPT1b overexpression decreased L-carnitine levels and inhibited the Jak2/Stat3 signaling pathway, which was associated with the pathogenesis of myocardial hypertrophy." (PMID 40093901, 2025). "In this study, using LAD ligation in HSF1 KO and TG mice, together with hypoxic treatment in NRCMs infected with adenovirus of HSF1 SiRNA, we uncovered that deficiency of HSF1 deteriorated cardiac hypertrophy and cardiac dysfunction after MI through enhancing the activity of JAK2/STAT3 signalling." (PMID 29992755, 2018). "Pressure overload induces cardiac hypertrophy through activation of Janus kinase 2 (Jak2), however, the underlying mechanisms remain largely unknown." (PMID 25380525, 2014). "Ying and colleagues examined how Janus kinase 2 (Jak2) contributes to cardiac hypertrophy from pressure overload." (PMID 40660005, 2025). "CHACR attenuated cardiac hypertrophy by increasing the expression of CPT1b, which is involved in regulation of the Jak2/Stat3 pathway, demonstrating the participation of this circRNA-mediated protein mechanism in the pathogenesis of cardiac hypertrophy." (PMID 40093901, 2025). "CHACR, which was mainly expressed in the cytoplasm, bound directly to CPT1b and upregulated its expression, which consequently inhibited L-carnitine level to inactivate the Jak2/Stat3 pathway, thereby attenuating cardiac hypertrophy (Graphical abstract)." (PMID 40093901, 2025). "On this foundation, we proved that CPT1b suppressed Jak2/Stat3 signaling pathway to aggravate cardiac hypertrophy." (PMID 40093901, 2025). "STAT3 is regarded as the most important downstream factor of JAK2 in the initiation and development of cardiac hypertrophy." (PMID 39294131, 2024). "Numerous studies have shown that the JAK2/STAT3 pathway participates in the pathology of cardiac hypertrophy and HF." (PMID 39294131, 2024). "Serum accumulation of retinol in CKD prompts myocardial hypertrophy and fibrosis by activating JAK2/STAT5." (PMID 37564202, 2023). "Serum accumulation of retinol in CKD prompts myocardial hypertrophy and fibrosis by activating JAK2 and phosphorylating STAT5." (PMID 37564202, 2023). "Collectively, our data reveals a therapeutic property of pirfenidone on ISO-induced cardiac hypertrophy in mice via inhibition of the JAK2/STAT3 pathway." (PMID 35609321, 2022). "Then, the phosphorylation of STAT3(Tyr705) and JAK2(Tyr1007/1008) were examined to elucidate the mechanism which PM alleviates cardiac hypertrophy." (PMID 35365949, 2022). "Numerous studies have shown that the JAK2/STAT3 signalling pathway is a key signal transduction pathway known to participate in the progression of cardiac hypertrophy." (PMID 35365949, 2022). "CHR alleviates isoproterenepin-induced cardiac hypertrophy by repressing JAK2/STAT3 pathway activation." (PMID 35599576, 2022). "Protocatechuic aldehyde protects against ISO-induced cardiac hypertrophy via inhibition of the JAK2/STAT3 signaling pathway." (PMID 36670950, 2022).
cardiac hypertrophy (continued). "Our results collectively demonstrated that PM prevented cardiac hypertrophy in vivo and in vitro by inhibiting the JAK2/STAT3 pathway." (PMID 35365949, 2022). "Based on these results, we concluded that loganin mitigated Ang II–provoked cardiac hypertrophy at least partially through inhibiting the JAK2/STAT3 and NF-κB signaling pathways." (PMID 34194329, 2021). "The latest research found that the JAK2/STAT3 pathway participates in the process of AngII-induced myocardial remodeling by promoting myocardial hypertrophy and fibrosis." (PMID 34764873, 2021). "Among them, JAK2 and STAT3 have been attracted our attention because the JAK2/STAT3 pathway is closely related to myocardial hypertrophy and fibrosis." (PMID 34764873, 2021). "To investigate the mechanisms of loganin acting on cardiac hypertrophy, we detected effects of loganin on the JAK2/STAT3 and NF-κB signaling pathways, which are involved in cardiac hypertrophy and inflammation induced by Ang II." (PMID 34194329, 2021). "Based on these results, we conclude that loganin mitigates Ang II–induced cardiac hypertrophy at least partially through inhibiting the JAK2/STAT3 and NF-κB signaling pathways." (PMID 34194329, 2021). "In NE-induced cardiac hypertrophy, the protein expression of JAK2 and STAT3 is significantly upregulated, further promoting the development of cardiomyocyte hypertrophy." (PMID 34221090, 2021). "Combining with TG-101348 and JSI-124, the specific inhibitor of JAK2, we confirmed that the inhibitory effect of magnolol on myocardial hypertrophy and fibrosis is related to the inhibition of the JAK2/STAT3 signaling pathway." (PMID 34764873, 2021). "STAT3 is the most important effector of the JAK2 in the initiation and development of cardiac hypertrophy." (PMID 30940158, 2019). "Increasing evidence suggests that the JAK2/STAT3 pathway is involved in the development of cardiac hypertrophy." (PMID 30940158, 2019). "As JAK2 is critically involved in the cardiac hypertrophy, we measured the phosphorylation of JAK2 in both the MI mouse hearts and the hypoxia‐treated NRCMs." (PMID 29992755, 2018). "Previous reports have also suggested that JAK2/STAT3 promoted the transition of cardiac hypertrophy to failure." (PMID 28686615, 2017). "Pressure overload-induced cardiac hypertrophy is mediated partly by activation of Janus kinase 2 (Jak2)." (PMID 25380525, 2014). "On the other hand, treatment with the Jak2 inhibitor AG-490 prevented the hypertrophic response, indicating that Jak2 is important in the development of cardiac hypertrophy." (PMID 25380525, 2014). "Significantly, we found that AB-induced HDAC2 nuclear exportation in hearts, which was almost blocked by Jak2 inhibitor AG-490, the latter also prevented cardiac hypertrophy." (PMID 25380525, 2014). "Therefore, we focused on Jak2/Stat3 signaling pathway, which was a vital signaling pathway involved in cardiac hypertrophy." (PMID 40093901, 2025). "Thus, to explore the downstream regulator of ALKBH5 in cardiomyocyte hypertrophy, the JAK2/STAT3 pathway piqued our interest due to its pivotal role in cardiac hypertrophy." (PMID 39294131, 2024). "JAK2/STAT5 signal activated by retinol may be the key pathways prompts cardiac hypertrophy, interstitial fibrosis and HFpEF progression behind the scenes." (PMID 37564202, 2023). "JAK2 could regulate cardiac contractility and promote the transition from cardiac hypertrophy to cardiac dysfunction." (PMID 36670950, 2022). "Administration of magnolol and TG-101348 or JSI-124 (both JAK2 selective inhibitors) could prevent myocardial hypertrophy and fibrosis, accompanied by the decrease in the phosphorylation level of JAK2 and STAT3." (PMID 34764873, 2021). "In addition, IL-6 activates the JAK2/STAT3 signaling pathway in cardiac hypertrophy, and it is produced by macrophages and cardiomyocytes in response to hypertrophic stimulus." (PMID 34194329, 2021).
cardiac hypertrophy (continued). "Indeed, cardiac hypertrophy due to increased fibroblast proliferation downstream of increased TWEAKR activity is supported by JAK2/STAT3 mediated hypertrophy in atrial myocytes." (PMID 33042024, 2020). "Our data collectively demonstrated that HSF1 is critically involved in the pathological cardiac hypertrophy after MI via modulating JAK2/STAT3 signalling and may constitute a potential therapeutic target for MI patients." (PMID 29992755, 2018). "Jak2 plays an important role in the development of cardiac hypertrophy." (PMID 25380525, 2014). "Furthermore, CHACR inhibited the Jak2/Stat3 pathway by regulating CPT1b expression, which may be involved in the pathogenesis of cardiac hypertrophy." (PMID 40093901, 2025). "In vivo, PM reversed TAC‐induced cardiac hypertrophy, as determined by down‐regulating ratios of heart weight to body weight (HW/BW), heart weight to tibial length (HW/TL) and expressions of hypertrophy‐related proteins accompanied by the inhibition of the JAK2/STAT3 pathway." (PMID 35365949, 2022). "Although our results might not exclude other mechanisms by which HSF1 suppresses cardiac hypertrophy induced by ischaemia, the inhibitory effect of HSF1 on the development of cardiac hypertrophy seems to be largely dependent on the repression of JAK2/STAT3 by HSF1." (PMID 29992755, 2018). "The activation of the JAK2/STAT3 signaling pathway was detected in hypertrophic hearts elicited by isoproterenol and the inhibition of the activities of JAK2 and STAT3 mitigated myocardial hypertrophy." (PMID 40271123, 2025). "As is known, activation of Jak2/Stat3 signaling pathway would lead to the production of factors such as ANP/BNP, which are vital in cardiac hypertrophy 30,31." (PMID 40093901, 2025). "Numerous studies have shown the involvement of the janus kinase 2 (JAK2)-signal transducers and activators of transcription 3 (STAT3) pathway in the pathology of cardiac hypertrophy and HF." (PMID 39294131, 2024). "The JAK2/STAT3 signaling pathway is a common signal transduction pathway in the development of HF and plays a crucial role in myocardial hypertrophy." (PMID 36670950, 2022). "Modern pharmacological studies have established that the JAK2/STAT3 signalling pathway participates in the progression of myocardial ischaemia, cardiac hypertrophy and heart failure." (PMID 35365949, 2022). "In summary, our study provides evidence that PM protects against pathological cardiac hypertrophy by inhibiting levels of the STAT3 phosphorylation and nuclear translocation to suppress the activation of JAK2/STAT3 signalling pathway." (PMID 35365949, 2022). "For instance, JAK2/STAT3 and nuclear factor-κB (NF-κB) signaling pathways are closely involved in the development of cardiac hypertrophy." (PMID 34194329, 2021). "According to our in vitro and in vivo data, FNDC5 absence/knockdown led to an enhanced phosphorylation level of JAK2 and STAT3 under high lipid treatment (HFD/PA) accompanied by aggravated inflammation, oxidative stress and cardiac hypertrophy." (PMID 30940158, 2019). "Growing evidence points to the regulatory capacity of JAK2/STAT3 pathway on inflammation-related diseases and cardiac hypertrophy." (PMID 30940158, 2019). "The inhibitory effect of AG490 in JAK2/STAT signaling has been found in tissues with different pathological stresses, including myocardial hypertrophy, liver ischemia-reperfusion, traumatic brain injury, and chronic renal disease." (PMID 27274711, 2016). "In order to test the role of Jak2 and HDAC2 in cardiac hypertrophy response, siRNA strategy was utilized to selectively knockdown Jak2 or HDAC2 in H9c2 cardiomyocytes." (PMID 25380525, 2014). "Previous studies also showed that ROS activate Jak2 and thereafter STAT3 involved in cardiac hypertrophy." (PMID 25247053, 2014).
cardiac hypertrophy (continued). "Additionally, ALKBH5 mediates the demethylation of STAT3 and regulates the expression of inflammatory factors (such as IL-6 and TNF-α) by activating the JAK2/STAT3 signaling pathway, thereby affecting the progression of cardiac hypertrophy." (PMID 40290189, 2025). "Furthermore, Ang II employs the JAK2/STAT3 and NF-κB signaling pathways in mediating inflammatory response and cardiac hypertrophy." (PMID 34194329, 2021). "In addition, acute pressure overload and mechanical stress can activate JAK1, JAK2, TYK2, STAT2, STAT3, and the IL-6 family (including cardiotrophin 1, LIF, and IL-6 itself), and it has been suggested that this activation is a potentially important mechanism of myocardial hypertrophy." (PMID 36671504, 2023).
Hypertension (31 papers, 2013 to 2025). The presence of chronic increased pressure in the systemic arterial system. "Multivariable analysis confirmed age ≥60 years (p = 0.001), male gender (p = 0.01), JAK2 mutational status (p = 0.01), hypertension (p = 0.01), and arterial thrombosis history (p = 0.02) as independent predictors of future arterial thrombotic events." (PMID 38238303, 2024). "In VSMCs, Ang II induces JAK2, which activates RhoA guanine nucleotide exchange factor I, Arhgef1, which eventually activates RhoA signaling and causes hypertension." (PMID 36324691, 2022). "In VSMCs, stimulation of JAK2 by Ang II leads to activation of RhoA guanine nucleotide exchange factor I, Arhgef1, which, in turn, stimulates RhoA signaling, causing hypertension." (PMID 31703282, 2019). "Jak2 is expressed in nearly every tissue in the body and it has been implicated in a number of other pathologies including renal injury, hypertension, and heart failure." (PMID 23544085, 2013). "According to studies, there may be a link between JAK2 gene variants and an increased risk of hypertension." (PMID 37571339, 2023). "We specifically chose to examine ARHGEF1 in more detail because it has previously been implicated in AngII-induced hypertension and shown to be tyrosine phosphorylated by Janus kinase-2 (JAK2) in mesenteric artery as an essential step in its activation by AngII." (PMID 28673614, 2017). "Interestingly, the VIMP analysis has also identified an association between JAK2 and hypertension, which is in line with a recent experimental finding that the activation of JAK-STAT pathway plays an important role in the development of Angiotensin II-dependent hypertension." (PMID 35896580, 2022). "Even more, previous studies found AG 490, widely recognized as an inhibitor of JAK2, was proven to prevent hypertension." (PMID 38474730, 2024). "Changes in several genes, including JAK2, PTGS2, and HIF1A, which have also been connected to the emergence of hypertension, have been linked to resistance to these inhibitors." (PMID 37571339, 2023). "The VIMP results identified other potential associations that will not be able to be confirmed until new clinical evidence is published, e.g., the association between hypertension and JAK family kinases including JAK2 and JAK3." (PMID 35896580, 2022). "Experiments showed that the AngII induced hypertension was relieved in the IL-6−/− mice, suggesting a key role IL-6 plays in the induction of hypertension depending on JAK2/STAT3 pathway in the kidney." (PMID 36195874, 2022). "In vivo results also shown that modulation of JAK2 and AT1Rs reduces the progression of hypertension and proteinuria in diabetic renal dysfunction." (PMID 36324691, 2022). "It has been observed that the JAK2/STAT3 pathway plays an important role in regulating age- and hypertension-associated rise of aortic stiffness." (PMID 35694160, 2022). "IL6 can influence the development of Ang II-mediated hypertension by intervening the JAK2/JAK3 pathway." (PMID 35360657, 2022). "There is evidence that AG490, a JAK2 inhibitor, reduced Ang II-induced contraction in normotensive rat thoracic aortas and suppressed Ang II-induced hypertension." (PMID 34439742, 2021). "For the proof-of-concept trial, we successfully selected telmisartan, a clinically used medicine against hypertension, as the strongest JAK2 inhibitor." (PMID 33917914, 2021). "Experimental evidence from both in vivo and in vitro studies established that activation of the JAK2/STAT3 pathway by Ang II plays a central role in the development of Ang II-dependent hypertension." (PMID 31703282, 2019). "In vivo studies also showed that inhibition of JAK2 and AT1Rs significantly reduced the development of both hypertension and proteinuria in diabetic nephropathy." (PMID 31703282, 2019).